BMP2 (bone morphogenetic protein 2)
Description:
Growth factor of the TGF-beta superfamily that plays essential roles in many developmental processes, including cardiogenesis, neurogenesis, and osteogenesis. Induces cartilage and bone formation. Initiates the canonical BMP signaling cascade by associating with type I receptor BMPR1A and type II receptor BMPR2. Once all three components are bound together in a complex at the cell surface, BMPR2 phosphorylates and activates BMPR1A. In turn, BMPR1A propagates signal by phosphorylating SMAD1/5/8 that travel to the nucleus and act as activators and repressors of transcription of target genes. Also acts to promote expression of HAMP, via the interaction with its receptor BMPR1A/ALK3. Can also signal through non-canonical pathways such as ERK/MAP kinase signaling cascade that regulates osteoblast differentiation. Also stimulates the differentiation of myoblasts into osteoblasts via the EIF2AK3-EIF2A-ATF4 pathway by stimulating EIF2A phosphorylation which leads to increased expression of ATF4 which plays a central role in osteoblast differentiation. Acts as a positive regulator of odontoblast differentiation during mesenchymal tooth germ formation, expression is repressed during the bell stage by MSX1-mediated inhibition of CTNNB1 signaling (By similarity).
Synonyms: BMP2A; BDA2; SSFSC; SSFSC1
Tractability: Small molecule: a structure with a bound ligand is known. Antibody: its Gene Ontology location is reachable by antibodies, with high confidence; UniProt places it where antibodies can reach, with medium confidence; UniProt predicts a signal peptide or a membrane-spanning region. PROTAC: ubiquitination databases record sites on it.
Target class: Enzyme; Metallo protease M12A subfamily; Metallo protease; Protease; Metallo protease MAM clan
Gene: Protein-coding gene on chromosome 20 (6,767,686 to 6,780,251, forward strand). Ensembl gene ENSG00000125845.
Subcellular location: Secreted
Subcellular location (Human Protein Atlas): Vesicles; Basal body; Cytosol; Nucleoplasm; Plasma membrane; Primary cilium; Primary cilium tip; Primary cilium transition zone; Predicted to be secreted
Pathways (Reactome):
Gene expression (Transcription): Regulation of RUNX2 expression and activity; Transcriptional regulation by RUNX2
Extracellular matrix organization: Molecules associated with elastic fibres
Signal Transduction: Signaling by BMP
Gene Ontology:
Molecular function: BMP receptor binding; co-receptor binding; cytokine activity; growth factor activity; phosphatase activator activity; protein binding; signaling receptor binding; receptor ligand activity
Biological process: BMP signaling pathway; cardiac epithelial to mesenchymal transition; cardiac muscle cell differentiation; cardiocyte differentiation; cellular response to BMP stimulus; chondrocyte differentiation; endodermal-mesodermal cell signaling; epithelial to mesenchymal transition; heart development; heart induction; intracellular iron ion homeostasis; lung vasculature development; mesenchymal cell differentiation; mesenchyme development; negative regulation of aldosterone biosynthetic process; negative regulation of calcium-independent cell-cell adhesion; negative regulation of canonical Wnt signaling pathway; negative regulation of cardiac muscle cell differentiation; negative regulation of cell cycle; negative regulation of cell population proliferation; negative regulation of cortisol biosynthetic process; negative regulation of DNA-templated transcription; negative regulation of fat cell differentiation; negative regulation of gene expression; negative regulation of insulin-like growth factor receptor signaling pathway; and 69 more
Cellular component: BMP receptor complex; cell surface; extracellular region; protein-containing complex; plasma membrane
Genetic constraint (gnomAD): Loss-of-function variants: 2 observed, 29.58 expected, observed/expected ratio (o/e) 0.0676, 90% interval 0.027 to 0.21. The upper end of that interval is the gene's LOEUF score, 0.21, which puts it in group 1 of 6, group 1 being the genes least tolerant of losing a copy. Missense variants: 437 observed, 529.5 expected, observed/expected ratio (o/e) 0.83, 90% interval 0.76 to 0.89. Synonymous variants: 218 observed, 204.79 expected, observed/expected ratio (o/e) 1.06, 90% interval 0.95 to 1.19.
Homologues: Orthologues: chimpanzee BMP2 (99% identical), macaque BMP2 (99% identical), guinea pig BMP2 (95% identical), dog BMP2 (94% identical), pig BMP2 (93% identical), rat Bmp2 (92% identical), mouse Bmp2 (91% identical), tropical clawed frog bmp2 (73% identical), rabbit BMP2 (66% identical), zebrafish bmp2b (66% identical), zebrafish bmp2a (64% identical). Paralogues in human: BMP4 (63% identical), BMP6 (33% identical), BMP10 (32% identical), BMP7 (30% identical), BMP5 (30% identical), GDF2 (30% identical), BMP8A (30% identical), BMP8B (30% identical), GDF7 (30% identical), GDF6 (28% identical), GDF5 (28% identical), GDF3 (25% identical), and 19 more.
Diseases named in the same sentence as BMP2 in open-access papers:
BMP2 is named in the same sentence as 376 diseases in open-access papers, as found by Europe PMC text mining. Sharing a sentence is not in itself a finding about the gene and the disease. The quoted sentences say what the papers report.
osteoporosis (140 papers, 2005 to 2026). A condition of reduced bone mass, with decreased cortical thickness and a decrease in the number and size of the trabeculae of cancellous bone (but normal chemical composition), resulting in increased fracture incidence. "The association of noncoding variants in the 3’ region of BMP2 resulting in nonsyndromic sagittal craniosynostosis points to another interesting intersection with osteoporosis." (PMID 36225206, 2022). "rs15705, for instance, is identified in the BMP2 3′-UTR as an osteoporosis-associated variant in Icelandic patients." (PMID 34537818, 2021). "In this study, PMT ameliorated bone loss in osteoporosis by activating osteoblastic markers such as BMP-2 signaling pathway, leading to improving bone integrity." (PMID 33841161, 2021). "This combination will reduce the risk of side effects from BMP2 in the treatment of bone diseases such as osteoporosis." (PMID 31661767, 2019). "High dose BMP2 or BMP7 need to be administrated systemically to treat bone loss or osteoporosis, that posses a risk of systemic adverse effect." (PMID 30159139, 2018). "Previous research has also linked osteoporosis with specific polymorphisms in the BMP-2 gene, confirming an association with osteoporosis." (PMID 28474578, 2017). "Taken together, these results indicate that BMP2 therapeutic inhibition of KDM5A (by shRNA or inhibitor of its methytranferase activity) was able to partly counteract the bone loss observed in osteoporosis." (PMID 27512956, 2016). "A previous study showed linkage of osteoporosis to specific polymorphisms in the BMP-2, ALP, and OPN genes, revealing that they are osteoporosis-associated genes." (PMID 24156308, 2013). "Recently, variation in the gene encoding BMP2 was found to be associated with osteoporosis in a study employing whole genome linkage and subsequent positional cloning." (PMID 15752431, 2005). "In the current study, we replicated the association between the Ser37Ala variant in BMP2 and measures of osteoporosis in an international family-based sample ascertained via low BMD probands." (PMID 15752431, 2005). "Several investigations have consistently shown that NELL-1 plays a crucial role in the osteogenic differentiation of osteoblasts, and it has been found to interact synergistically with other genes implicated in the development of osteoporosis, such as Bone Morphogenetic Protein 2 (BMP2)." (PMID 39255297, 2024). "Melatonin improves age-related bone loss and osteoporosis by upregulating the expression of BMP2." (PMID 35359458, 2022). "Our data reveled that Ps-GOS significantly up-regulates the expression of Wnt5a, LRP5, β-catenin, and Fzd4 mRNA, in MC3T3-E1 cells, suggesting that Ps-GOS may prevent bone loss in osteoporosis through Wnt/β-catenin together with BMP-2 signaling pathways." (PMID 32012654, 2020). "The BMP-2 gene has been genetically linked to osteoporosis and osteoarthritis." (PMID 28797104, 2017). "The studies linking Bmp2 polymorphisms and osteoporosis are controversial and contradictory." (PMID 24837969, 2014). "Similarly, rs2288377, rs35767, and rs2229765 polymorphisms within Insulin-like growth factor (IGF) genes, which are critical regulators for bone cell function, and T116G and G287T polymorphisms in exon 2, and A224T in exon 3 of BMP-2 gene, have been strongly associated with osteoporosis." (PMID 35163424, 2022). "Our findings from previous and current study suggest that combination of ATRA and BMP2/7 could be a novel approach to treat hyperactive osteoclast-induced bone loss such as in inflammation-induced severe osteoporosis and bone loss caused by cancer metastasis to bone." (PMID 30159139, 2018). "It has been reported that the transcription of BMP2 is regulated by an enhancer region located 156.3 kb from the promoter of BMP2 and that its noncoding sequence variants may influence BMP2 transcription and thus may contribute to bone mass and osteoporosis." (PMID 24710560, 2014).
osteoporosis (continued). "For example, in the BMP2 3'UTR, the SNP rs15705 has been identified as a variant associated with osteoporosis." (PMID 40612684, 2025). "The study also explored the involvement of BMP2/Smads signalling in aucubin promoting the osteogenesis of hBMSCs and evaluated the effects of aucubin intervention on osteoporosis using an ovariectomised rat model." (PMID 39823248, 2025). "Overall, the dual activation by SIM of the Wnt/β-catenin and BMP2 pathways contributes to osteogenesis, offering promising potential applications in bone defect repair and osteoporosis treatment." (PMID 40416784, 2025). "Previous research demonstrated the formulation's efficacy in improving bone health in osteoporosis models by upregulating osteogenic markers such as BMP‐2 and OPN." (PMID 40357339, 2025). "The direct relationship between miRNA dynamics and their regulation by BMP2 in osteoporosis is poorly understood; however, it is known that miR-370 and miR-138 expression levels tend to increase when BMP2 levels decrease in colorectal cancer." (PMID 39997614, 2025). "Eucommia ulmoides Oliver polysaccharide alleviates glucocorticoid-induced osteoporosis by stimulating bone formation via ERK/BMP-2/SMAD signaling." (PMID 40786053, 2025). "In line with our observations, other studies have reported that PEMF increases BMP-2 expression in disuse osteoporosis models." (PMID 41007168, 2025). "Overall, vanillin has bone-forming properties through the BMP2-mediated biological mechanism, indicating it as a bone-protective compound for bone health and bone diseases such as periodontitis and osteoporosis." (PMID 38675146, 2024). "A total of 387 circRNAs were found to be differentially expressed in osteoporosis compared with healthy controls, with circDNAH14 (hsa_circ_0016624) preventing osteoporosis by regulating BMP2 via miR‐98 sponging." (PMID 39239069, 2024). "At the same time, we also found that Irisin treatment significantly increased the expression of osteogenic genes (Runx2, OSX, OCN, OPN, ALP and BMP2) in BMSCs of osteoporosis mice, while SB203580 strongly weakened this function of Irisin." (PMID 38500202, 2024). "Osteoblasts and osteocytes constitutively secrete BMP-2, which has been used as a therapy for bone fractures and diseases, such as osteoporosis, due to its osteogenic potential." (PMID 37888168, 2023). "Mechanistically, our study showed that reduced APPL1 impaired the osteogenic differentiation of mesenchymal stem cells by facilitating Matrix Gla protein expression to disrupt the BMP2 pathway in osteoporosis." (PMID 37187293, 2023). "17-β-estradiol was encapsulated in poly (D, L-lactide) (PLA-S) microspheres and locally applied to induce bone regeneration in OP (osteoporosis) female rats using PLGA (poly (lactic-co-glycolic acid))-PVA (polyvinyl alcohol) microspheres to load BMP-2." (PMID 36986842, 2023). "Rhizoma cibotii strengthens bones and tendons and treats osteoporosis by activating the BMP2/SMAD1 signaling pathway for osteogenesis." (PMID 38114998, 2023). "Mechanistically, reduced APPL1 impaired the osteogenic differentiation of MSCs by facilitating MGP expression to disrupt the BMP2 pathway in osteoporosis." (PMID 37187293, 2023). "Previous studies have shown that TFRD can treat osteoporosis in rabbits and rats through BMP-2 related signaling pathway." (PMID 35694251, 2022). "We have confirmed that the stem cell secretome includes OPG and BMP-2, two important factors in osteoporosis therapy." (PMID 35033095, 2022). "Osteo-F ameliorated bone loss by increasing bone forming molecules including BMP-2 and OPN in osteoporosis." (PMID 36387862, 2022). "By enhancing the activity of bone morphogenetic protein 2, parbendazole induces osteogenic differentiation, exerting its osteoporosis-prevention effects." (PMID 36081904, 2022). "Long non-coding RNA MSC-AS1 promotes osteogenic differentiation by binding miR-140-5p to upregulate BMP2, relieving osteoporosis." (PMID 35164658, 2022).
osteoporosis (continued). "We propose BMP2 as a potential drug target for treating bone metabolic diseases, such as osteoporosis." (PMID 35164658, 2022). "For instance, lncRNA MSC-AS1 promotes osteogenic differentiation by regulating bone morphogenic protein 2 (BMP2) expression through targeting miRNA-140-5p, thereby attenuating osteoporosis." (PMID 35226820, 2022). "Administration with piR-36741 mimic attenuated ovariectomy-induced osteoporosis in mice through METTL3-mediated m6A methylation of BMP2 transcripts." (PMID 35634512, 2022). "In conclusion, piRNA-36741 overexpression promoted osteogenic differentiation of BMSCs and mitigated ovariectomy-induced osteoporosis through METTL3-mediated m6A methylation of BMP2 transcripts." (PMID 34645714, 2021). "The addition of BMP-2 in osteoporosis rats significantly improved bone repair and enhanced new bone formation in the margins of the defect as well as intramembranous ossification zones by reducing mineralization of the newly formed bone." (PMID 34360948, 2021). "The researchers showed that circDNAH14 (circBase ID hsa_circ_0016624) prevented osteoporosis through the regulation of BMP2 via miR-98 sponging." (PMID 34482380, 2021). "These experimental results indicated that SR inhibits osteoclast differentiation and increases osteoblast activity in the OVX-induced osteoporosis model, and this effect is mediated by NFATc1 and BMP-2 similar to the in vitro experimental results." (PMID 35058781, 2021). "Factors thought to contribute to cage subsidence are the narrower 18 μm cages, osteoporosis, the use of bone morphogenetic protein (BMP-2), the use of standalone cages, and iatrogenic endplate violation." (PMID 33596403, 2021). "Previous research has shown that the inhibition of miR‐106b lightened hormone‐induced osteoporosis through the BMP2/SMAD signalling pathway." (PMID 32485091, 2020). "In the present study, we observed a significant decrease of H19 expression in postmenopausal osteoporosis patients and in BMP-2 induced BMSCs compared with controls, which was consistent with a former study." (PMID 31918667, 2020). "Due to its role in osteogenesis, the growth factor bone morphogenetic protein 2 (BMP‐2) is of tremendous interest for bone regenerative medicine, osteoporosis therapeutics, and beyond." (PMID 32775147, 2020). "The expression of miR-19b-3p was significantly up-regulated in postmenopausal osteoporosis patients and BMP-2 induced BMSCs." (PMID 31918667, 2020). "Potential treatments for osteoporosis, osteopenia, osteoarthritis, and coronary artery disease with BMP-2 and/or its signaling pathways are in development." (PMID 32933207, 2020). "Our results concluded that calcium supplement in combination of Sim activated BMP-2 in osteoblasts (through the BMP-Smad signaling pathway) was suggested to promote the formation of new bone to finally reverse the osteoporosis process in treated subjects." (PMID 32754265, 2020). "Regarding osteoporosis, several TGF-β superfamily members (TGFB1, BMP2, BMP4, and Sclerostin) have been implicated as candidate genes in osteoporosis." (PMID 33297501, 2020). "For example, MSC‐AS1 can promote the BMSCs osteogenic differentiation via repressing miR‐140‐5p to induce BMP2, which can alleviate osteoporosis progression." (PMID 32489020, 2020). "Currently, treating patients with BMP2 in order to promote fracture healing is pointless if those patients are diagnosed with osteoporosis and already have a decreased response to BMP2." (PMID 31771161, 2019). "From a clinical perspective, these small molecules that regulate BMP2 activity provide powerful tools for the treatment of osteoporosis and fracture repair." (PMID 31661767, 2019). "Recently, a signaling disparity in bone marrow stromal cells within the bone morphogenetic protein pathway that led to decreased bone morphogenetic protein 2 responsiveness was identified in patients diagnosed with osteoporosis." (PMID 31771161, 2019).